NLRP3 (NLR family pyrin domain containing 3)
Diseases named in the same sentence as NLRP3 in open-access papers (continued):
Sharing a sentence is not in itself a finding about the gene and the disease.
tauopathy (continued). "To identify the potential role of NLRP3 acetylation in inflammasome activation in transgenic mice and patients with Tauopathy, we analysed hippocampal samples from 3xTg‐AD transgenic mice (9‐month old)." (PMID 38488468, 2024). "In conclusion, our findings provide evidence for a novel role of Tau in the regulation of microglia activation through acetylating NLRP3, which has potential implications for early intervention and personalised treatment of AD and related Tauopathies." (PMID 38488468, 2024). "Meanwhile, we also verified that hippocampal NLRP3 acetylation level was up‐regulated in Tauopathy transgenic mice and AD patients." (PMID 38488468, 2024). "Our key finding is that simultaneous, targeted downregulation of both NF-κB and NLRP3 via Nanoligomers reduces neuroinflammation and improves cognitive function in mouse models of both aging and tauopathy." (PMID 39068433, 2024). "• NLRP3 inflammasome is activated with increased NLRP3 acetylation in Tauopathy transgenic mice and AD patients." (PMID 38488468, 2024). "Anyway, deficiency of NLRP3 reduced the number of AT8-positive neurons in the hippocampus, indicating the attenuation of tauopathy, in tau-transgenic mice (one-way ANOVA, p < 0.001)." (PMID 39539344, 2024). "As the drive factor, Tau/pTau‐induced NLRP3 acetylation is thus a valuable target for early intervention of AD and related Tauopathies." (PMID 38488468, 2024). "Together, these data suggest that Tau and pTau proteins which increase in early stage of Tauopathy promote NLRP3 acetylation and activate NLRP3 inflammasome." (PMID 38488468, 2024). "Expression of the microglial cells by tauopathies can directly activate the NF‐κB inflammation pathways and NLR family pyrin domain containing 3 (NLRP3) protein, leading to an increase in pro‐inflammatory cytokine and its secretion." (PMID 36949020, 2023). "Recently, the role of NLRP3 inflammasome in tauopathy-induced neurodegeneration attracts extensive attention." (PMID 35993019, 2022). "Most recently, it has been demonstrated that NACHT, LRR, and PYD domains-containing protein 3 (NALP3/NLRP3) inflammasome activation plays a vital role in the pathogenesis of tauopathies." (PMID 32752058, 2020). "Recently, it was reported that disruption of the NLRP3 inflammasome, which reduces conversion of pro-IL-1β to mature IL-1β, among other actions, ameliorates the phenotype of both mouse models of amyloidosis and models of tauopathy." (PMID 41191631, 2025). "We further identified that Tau and pTau proteins, which increase at the early stage of Tauopathies significantly promoted NLRP3 acetylation and inflammasome activation in cells, and this effect was dependent on the Tau–K18 functional domain which harbour the acetyltransferase activity." (PMID 38488468, 2024). "Based on these findings, we propose that specific type(s) of Tau/pTau may directly acetylate NLRP3 to promote microglial inflammasome activation in Tauopathies." (PMID 38488468, 2024). "In the present study, we evaluated the efficacy of targeting both NF-κB and NLRP3 in brain aging and tauopathy by treating both old wildtype mice and transgenic rTg4510 mice (a model of tauopathy commonly used in neurodegeneration research) with our Nanoligomer cocktail." (PMID 39068433, 2024). "Since Tau was identified as a bona fide acetyltransferase with enzymatic activity resides within the microtubule‐binding regions, it is thus reasonable to speculate that Tau protein may induce NLRP3 acetylation in Tauopathies." (PMID 38488468, 2024). "Summing up, NLRP3 inflammasome targeting might hinder AD’s etiopathogenetic tripod, i.e., Aβs, p-Taues, and neuroinflammation, and beneficially affect tauopathies too." (PMID 37189617, 2023). "FX5 ameliorated synaptic impairment through GR/BDNF/TrkB/CREB pathway, protected against neuronal apoptosis by repressing GR/PI3K/AKT/GSK3β pathway-mediated tauopathy and subsequent ER stress and repressed inflammation through GR/NF-κB/NLRP3/ASC/Caspase-1 pathway." (PMID 35260821, 2022).
tauopathy (continued). "One of the latest reports demonstrated that trazodone, an antidepressant with hypnotic efficacy in dementia, can reduce disease-related cellular pathways, including the NLRP3 inflammasome expression, and improve memory and sleep in male rTg4510 mice with a tauopathy-like phenotype." (PMID 35883667, 2022). "NLRP3 inflammasome depletion protected tauopathy mice from cortical tau accumulation." (PMID 35273086, 2022). "They illustrate the Aβ-cascade hypothesis in AD that neurofibrillary tangles develop downstream of Aβ-induced microglial activation, which involves NLRP3 inflammasome activation in the pathogenesis of tauopathies." (PMID 33551822, 2020). "Tau-induced NLRP3–ASC inflammasome activation provides a compelling mechanism for the association between microglial activation and Tau pathology observed in AD and related Tauopathies." (PMID 30721409, 2019). "To explore whether blocking NLRP3 acetylation and NLRP3 inflammasome activation induced by Tau can prevent microgliosis in Tauopathies, we designed a peptide TNB (LEDLEDVDLKKFKMHLEDYPP) based on region of NLRP3 binding with Tau to competitively inhibit Tau–NLRP3 interaction." (PMID 38488468, 2024). "With the emergence of brain-penetrant Nlrp3 inhibitors, future investigations should focus on examining whether pharmacological targeting of the Nlrp3 inflammasome can effectively suppress the formation of neurofibrillary tangles in AD and other tauopathies." (PMID 38352874, 2024). "In addition, felodipine treatment decreased NLRP3 mRNA levels in the cortex and hippocampus region of Tau Tg PS19 mice, suggesting that felodipine treatment may downregulate tauopathy-associated neuroinflammatory responses by inhibiting NLRP3 expression." (PMID 39223564, 2024). "We asked whether NLRP3 regulates vasculature under tauopathy." (PMID 39539344, 2024). "However, Nlrp3 deficiency did not mitigate tauopathy or neurodegeneration in P301S mice in vivo, showing only a minor effect on plasma neurofilament (NF-L) levels." (PMID 39381137, 2024). "Then, to provide translational relevance to this finding, we performed a longer intervention (proportional to that which might be conducted in older adults), in which we treated both old and tauopathy model mice with NF-κB/NLRP3-targeting Nanoligomers for one month." (PMID 39068433, 2024). "Finally, given the protective effects of NF-κB/NLRP3-targeting Nanoligomers in both old wildtype and tauopathy mice, along with evidence that aging and tauopathy may intersect, we used transcriptomics (RNA-seq) to provide insight into conserved mechanisms of action." (PMID 39068433, 2024). "They showed that following microglial endocytosis and lysosomal sorting, prion-like Tau seeds activated NLRP3 inflammasome signaling in the THY-Tau22 transgenic mouse line, a tauopathy-model animal." (PMID 37189617, 2023). "Subsequent studies highlighted the importance of the NLRP3 inflammasome in tauopathy, as the absence of NLRP3 improved the neurodegenerative phenotype in Tg-TAUP301S mice, as well as TAU propagation and hippocampal atrophy." (PMID 41486173, 2026). "We found that NF-κB/NLRP3-targeting Nanoligomer treatment reduced almost all of these cytokines, with PCA showing a marked reversal of overall cytokine patterns in both aged and tauopathy mice." (PMID 39068433, 2024). "The findings identified that p-tau has a triggering role in the modulation of neuroinflammation and spatial memory in an NLRP3-dependent manner, and suggest that treatment with HMGB1 inhibitors may be a better therapeutic strategy for tauopathies." (PMID 34539383, 2021). "The NLRP3–ASC inflammasome (iv), scrutinized as therapeutic target for many disorders and previously identified as Aβ-related therapeutic target, is herewith identified as a target for Tauopathies including AD." (PMID 30721409, 2019).
tauopathy (continued). "While activation of NLRP3–ASC inflammasome in primary Tauopathy patients remains to be demonstrated, it must be noted that Tau has been detected in microglia, in Tauopathy patients, and IL-1β levels were increased in brains of Tauopathy patients." (PMID 30721409, 2019). "However, the precise downstream mechanism by which NLRP3 disruption alleviates tauopathy is not known." (PMID 41191631, 2025). "Thus, the relationship between NLRP3 inflammasome activation and enhanced amyloidosis and tauopathy need not passage through IL-1β." (PMID 41191631, 2025). "Overall, our data indicate that extracellular tau protein stimulates microglia to phagocytose live neurons via Toll-like 4 receptor–NLRP3 inflammasome–caspase-1 axis and NADPH oxidase, each of which may serve as a potential molecular target for pharmacological treatment of tauopathies." (PMID 37402829, 2023). "The NLRP3 inflammasome, the autophagy-lysosomal pathway, CX3CL1 signaling pathway, and ApoE4 are all therapeutic targets that could yield potential new treatments for tauopathies." (PMID 33672982, 2021). "Furthermore, our data suggest that reduced canonical IL-1β signaling may not be responsible for the observed effects of NLRP3 disruption in mouse models of tauopathy." (PMID 41191631, 2025). "However, although NF-κB and NLRP3 signaling pathways are interconnected, no studies have investigated the effects of simultaneously targeting both of these proteins in old and/or tauopathy mice." (PMID 39068433, 2024).
dermatitis (30 papers, 2016 to 2026). An inflammatory process affecting the skin. "The pathogenic T cells which secrete cytokines can activate the NLRP3 inflammasome of keratinocyte, then caspase-1 mediated pro IL-1β cleavage will produce active IL-1β exacerbating skin inflammation." (PMID 37686332, 2023). "However, mice carrying GOF mutations in mouse Nlrp3 are protected from dermatitis when crossed onto a GSDMD-deficient background, implicating a pivotal role for GSDMD-mediated pyroptosis in the skin." (PMID 38649745, 2024). "Moreover, inactivation of the NLRP3 inflammasome has been implicated in the inhibition of cutaneous inflammation and consequent attenuation of skin disorders." (PMID 33634989, 2021). "In a chronic proliferative dermatitis animal model, Nlrp3- or Casp1- and -11-deficient mice showed reduced skin inflammation and delayed disease onset, suggesting that the inflammasome might be an important trigger for disease development." (PMID 32528469, 2020). "The importance of the innate immune response, particularly through γδ T cells, MCs, and the NLRP3 inflammasome, emerged as a central factor in amplifying skin inflammation." (PMID 40141293, 2025). "Mice treated with M. concanensis showed improved clinical symptoms, including reduced skin inflammation, dermatitis scores, and trans-epidermal water loss (TEWL), suggesting its effectiveness in alleviating AD through NLRP3 inflammasome inhibition." (PMID 40149610, 2025). "Chantui serves specific dermatitis cases, providing anti-inflammatory effects by regulating NLRP3 inflammasome activity." (PMID 41311842, 2025). "In conclusion, the EVEs decreased TPA-induced skin inflammation, which was associated with a decrease in the TLR4/NF-κB/NLRP3 inflammasome." (PMID 39684233, 2024). "Additional processes contribute to the dermatitis caused by the cpd mutation of Sharpin, including TLR3 signaling, NLRP3 inflammasome and IL-1β signaling, and IL-4 signaling." (PMID 38156288, 2024). "Our experimental results suggest that EVEs have the potential to reduce skin inflammation by inhibiting the TLR4/NF-κB/NLRP3 inflammasome pathway." (PMID 39684233, 2024). "This study aimed to investigate how D3T reduces skin inflammation and modulates Th17 cell differentiation by inhibiting NLRP3 inflammasome activation." (PMID 37686332, 2023). "Based on transcriptomic analyses, we have demonstrated that NF-κB signaling and NLRP3 inflammasome pathway were involved in P. acnes-induced and Bmal1-regulated skin inflammation." (PMID 35414779, 2022). "This study provided important complementary findings to previous investigations about the effect of mtROS and NLRP3 inflammasome on cutaneous inflammation, highlighting potential targets for effective treatment of inflammation‐related skin disorders." (PMID 33634989, 2021). "Other studies highlighted the anti-inflammatory role of Nrf2 signaling in reducing the levels of IL-1β and IL-6 to alleviate skin inflammation besides suppressing the activation of inflammatory NF-κB and NLRP3 pathways." (PMID 33424605, 2020). "The NLRP3 inflammasome is important in regulating disease progression (dermatitis) in Sharpincpdm mice." (PMID 27892465, 2016). "Previous studies have demonstrated that components of the TNF-signaling pathway, NLRP3 inflammasome and IL-1R signaling are required to provoke skin inflammation in Sharpincpdm mice." (PMID 27892465, 2016). "The NLRP3 inflammasome has also been reported to play a role in instigating skin inflammation in Sharpincpdm mice." (PMID 27892465, 2016). "Knockin of one such Nlrp3 mutation in mice phenocopies human CAPS, including severe dermatitis." (PMID 38649745, 2024). "In our study, the increased infiltration of macrophages into skin lesions and enhancement of IL-1β and NLRP3 expression suggested that inflammasome activation might be involved in exacerbating skin inflammation." (PMID 37964882, 2023).
dermatitis (continued). "Given that the NF-κB/NLRP3 axis is also involved in BMAL1 regulation of P. acnes-induced skin inflammation, we hypothesized that REV-ERBα may mediate the regulation of skin inflammation by BMAL1." (PMID 35414779, 2022). "NLRP3 inflammasome has also been demonstrated to be involved in dermatitis in Sharpincpdm mice." (PMID 35774778, 2022). "Because the NF-κB/NLRP3 axis is also involved in BMAL1 regulation of P. acnes-induced skin inflammation, we thus have tested whether REV-ERBα has a mediating role in the regulation of skin inflammation by BMAL1." (PMID 35414779, 2022). "Taken together, Bmal1 regulates P. acnes-induced skin inflammation via the NF-κB/NLRP3 axis." (PMID 35414779, 2022). "In addition, since it has been proven that NLRP3 inflammasomes participate in the pathological pathway of AD skin disorders, they can serve as a reference to screen for drugs that can target both skin inflammations and psychological stress." (PMID 36267291, 2022). "Additionally, our results strongly suggest that NLRP3 inflammasome activation is a trigger of dermatitis." (PMID 33520088, 2021). "Although mtROS are reported to play a critical role in the activation of NLRP3 inflammasome in several skin disorders induced by other irritants, our data indicated for the first time that mtROS were critical for NLRP3 inflammasome activation in NM‐stimulated keratinocytes." (PMID 33634989, 2021). "Impaired NLRP3 expression and function may be important for Staphylococcus aureus-induced chronic skin inflammation in AD." (PMID 32528469, 2020). "In IMQ-treated Nlrp3−/− mice, psoriasiform lesions were comparable to those of normal controls; however, caspase-1 activity in the skin was markedly decreased, indicating that the NLRP3 inflammasome was required for caspase-1 activation, but dispensable for skin inflammation." (PMID 32528469, 2020). "In consideration of NF-κB pathway was closely related to the activation of NLRP1 and NLRP3 inflammasomes in neurons 24, we further investigated whether NF-κB would also play a role in skin inflammation." (PMID 32922182, 2020). "The same trend was found in monocytes treated with Th2 milieu (LTA+alpha-toxin+IL-4, IL-5, and IL-13), suggesting that NLRP3 inflammasome impairment might contribute to skin inflammation in AD." (PMID 32528469, 2020). "IMQ-induced skin inflammation is independent on the NLRP3 inflammasome." (PMID 32528469, 2020). "Among all NLR members (22 up to now), NLRP3, NLRP1, NLRC4, and NLRP6 represent the most studied inflammasomes, involved in many inflammatory tissues pathologies, where NLRP3, NLRP1, and NLRC4 are mainly related to autoinflammatory skin disorders." (PMID 38068996, 2023). "AYZ inhibited the proliferation of mast cells, suppressed the activation of NLRP3 inflammasome and MAPKs/NF-kB signaling pathway, reduced the infiltration of inflammatory cells, and ameliorated DNCB-induced AD-like skin inflammation in mice." (PMID 36387340, 2022). "It was thus proposed that Bmal1 restrained P. acnes-induced skin inflammation via its target REV-ERBα, which acts on the NF-κB/NLRP3 axis to repress inflammation." (PMID 35414779, 2022). "Mechanistically, Bmal1 regulated P. acnes-induced skin inflammation via its target REV-ERBα, which acts on the NF-κB/NLRP3 axis to repress inflammation." (PMID 35414779, 2022). "Mechanistically, Bmal1 regulates P. acnes-induced skin inflammation via its target REV-ERBα, which acts on the NF-κB/NLRP3 axis to repress inflammation." (PMID 35414779, 2022). "We hypothesized that EVEs inhibit the TLR4/NF-κB/NLRP3 inflammasome, which decreases IL-1β, IL-18, and pyroptosis, thereby attenuating TPA-induced skin inflammation." (PMID 39684233, 2024). "Therefore, we propose that Bmal1 restrains P. acnes-induced skin inflammation via its target REV-ERBα, which acts on the NF-κB/NLRP3 axis to repress inflammation." (PMID 35414779, 2022).
dermatitis (continued). "highlighted a specific role of IL-1β, the downstream cytokine of NLRP3-GSDMD signaling, in provoking dermatitis in Sharpincpdm mice, suggesting that GSDMD may function as a potential checkpoint in CPD." (PMID 35774778, 2022). "AD-like dermatitis induced through FLG-deficiency was dependent on IL-1β and IL-1R1 signaling, but not NLRP3 inflammasome activation." (PMID 32528469, 2020). "Chemical inhibition of the inflammasome did not ameliorate the acute development of skin inflammation in Flgft/ft mice, which was consistent with our results on spontaneous and chronic inflammation in Nlrp3−/−Flgft/ft mice." (PMID 30937919, 2019). "Thus, we hypothesized that EVEs decrease skin inflammation by reducing HMGB1, S100A8, and the TLR4/NF-κB/NLRP3 inflammasome pathway, which eventually decreases TPA-induced skin inflammation." (PMID 39684233, 2024). "Although EVEs decrease oxidative stress, NF-κB, and the NLRP3 inflammasome in animal skin, it is not known whether they decrease TPA-induced skin inflammation." (PMID 39684233, 2024).